SYNJ1 (synaptojanin 1)
Description:
Phosphatase that hydrolyzes phosphate groups from the inositol ring of phosphoinositides and inositol phosphates, in a domain-specific manner. The 5-PPase domain catalyzes removal of the 5-phosphate from substrates such as phosphatidylinositol-4,5-bisphosphate (PtdIns(4,5)P2), phosphatidylinositol-3,4,5-trisphosphate (PtdIns(3,4,5)P3), inositol-1,4,5-trisphosphate (Ins(1,4,5)P3) and inositol-1,3,4,5-tetrakisphosphate (Ins(1,3,4,5)P4). The SAC domain hydrolyzes phosphates at the 3- and 4-positions of the inositol ring, targeting phosphatidylinositol-3-phosphate (PI(3)P), phosphatidylinositol-4-phosphate (PI(4)P), and phosphatidylinositol-3,5-bisphosphate (PI(3,5)P2). Plays a role in the phosphatidylinositol metabolic process during an unconventional endocytic mechanism, the ultrafast endocytosis where it participates in the rapide neck formation of the newly generated synaptic vesicle through its phosphoinositide 5-phosphatase activity (By similarity). Also, participates in the clathrin uncoating of synaptc vesicle formed via budding from synaptic endosomes after ultrafast endocytosis through combined activity of its phosphatase domains (By similarity). Additionally, regulates actin filament rearrangement by hydrolyzing PIP2 bound to actin regulatory proteins (By similarity).
Synonyms: INPP5G; PARK20; DEE53; EIEE53
Tractability: Small molecule: a structure with a bound ligand is known. PROTAC: ubiquitination databases record sites on it; its protein half-life has been measured; a small molecule that binds it is known.
Target class: Enzyme; Hydrolase
Gene: Protein-coding gene on chromosome 21 (32,628,757 to 32,728,040, reverse strand). Ensembl gene ENSG00000159082.
Subcellular location: Cytoplasm, perinuclear region; Presynapse; Membrane
Subcellular location (Human Protein Atlas): Cytosol; Nucleoplasm; Centrosome
Pathways (Reactome):
Metabolism: Synthesis of IP2, IP, and Ins in the cytosol; Synthesis of IP3 and IP4 in the cytosol; Synthesis of PIPs at the plasma membrane
Vesicle-mediated transport: Clathrin-mediated endocytosis
Gene Ontology:
Molecular function: inositol-1,4,5-trisphosphate 5-phosphatase activity; phosphatidylinositol phosphate phosphatase activity; phosphatidylinositol-3,4,5-trisphosphate 5-phosphatase activity; phosphatidylinositol-3,5-bisphosphate 3-phosphatase activity; phosphatidylinositol-3-phosphate phosphatase activity; phosphatidylinositol-4,5-bisphosphate 5-phosphatase activity; phosphatidylinositol-4-phosphate phosphatase activity; phosphatidylinositol-5-phosphate phosphatase activity; protein binding; phosphatidylinositol phosphate 4-phosphatase activity; phosphatidylinositol phosphate 5-phosphatase activity; phosphatidylinositol-3,5-bisphosphate 5-phosphatase activity; inositol-1,3,4,5-tetrakisphosphate 5-phosphatase activity; nucleic acid binding; phosphatase activity; RNA binding
Biological process: 1-phosphatidyl-1D-myo-inositol 4,5-bisphosphate catabolic process; learning; phosphatidylinositol catabolic process; phosphatidylinositol dephosphorylation; positive regulation of endosome organization; synaptic vesicle endocytosis; synaptic vesicle recycling; inositol phosphate metabolic process; membrane organization; neurotransmitter transport; phosphatidylinositol biosynthetic process; phosphatidylinositol metabolic process; synaptic vesicle priming; synaptic vesicle transport; synaptic vesicle uncoating; phosphatidylinositol-3-phosphate biosynthetic process
Cellular component: presynapse; clathrin coat of coated pit; cytoplasm; cytosol; membrane; membrane coat; microtubule; perinuclear region of cytoplasm; synaptic membrane; terminal bouton; vesicle membrane
Genetic constraint (gnomAD): Loss-of-function variants: 64 observed, 146.11 expected, observed/expected ratio (o/e) 0.44, 90% interval 0.36 to 0.54. The upper end of that interval is the gene's LOEUF score, 0.54, which puts it in group 2 of 6, group 1 being the genes least tolerant of losing a copy. Missense variants: 1,218 observed, 1,531.5 expected, observed/expected ratio (o/e) 0.8, 90% interval 0.76 to 0.83. Synonymous variants: 503 observed, 527.43 expected, observed/expected ratio (o/e) 0.95, 90% interval 0.89 to 1.03.
Gene-disease validity (ClinGen):
ClinGen rates the evidence that SYNJ1 causes each of these diseases.
genetic developmental and epileptic encephalopathy (autosomal recessive): Definitive. A complex neurodevelopmental disorder characterized by a range of developmental delays and epileptic encephalopathy phenotypes.
Homologues: Orthologues: chimpanzee SYNJ1 (99% identical), macaque SYNJ1 (99% identical), chimpanzee SYNJ1 (97% identical), dog SYNJ1 (95% identical), guinea pig SYNJ1 (95% identical), pig SYNJ1 (94% identical), mouse Synj1 (94% identical), rat Synj1 (92% identical), rabbit SYNJ1 (92% identical), tropical clawed frog synj1 (79% identical), zebrafish synj1 (71% identical), Drosophila melanogaster Synj (45% identical), and 5 more. Paralogues in human: SYNJ2 (47% identical), INPP5B (17% identical), INPP5D (16% identical), INPPL1 (15% identical), OCRL (15% identical), INPP5J (13% identical), INPP5E (11% identical), INPP5F (10% identical), FIG4 (9% identical), INPP5K (9% identical), SACM1L (7% identical), SH2D1B (3% identical), and 1 more.
Diseases named in the same sentence as SYNJ1 in open-access papers:
SYNJ1 is named in the same sentence as 73 diseases in open-access papers, as found by Europe PMC text mining. Sharing a sentence is not in itself a finding about the gene and the disease. The quoted sentences say what the papers report.
Parkinsonism (58 papers, 2013 to 2026). Characteristic neurologic anomaly resulting from degeneration of dopamine-generating cells in the substantia nigra, a region of the midbrain, characterized clinically by shaking, rigidity, slowness of movement and difficulty with walking and gait. "A mutation in the catalytic action of Sac1 domain in Synaptojanin-1 (SJ1) causes early-onset Parkinsonism." (PMID 38635628, 2024). "A third novel mutation (c.2515C>T) in the SYNJ1 gene was identified in a patient from Iran who presented asymmetric parkinsonism and seizures at 24 years of age." (PMID 39273702, 2024). "In parkinsonism-associated SYNJ1 R258Q mutation knock-in (KI) mice, SV endocytosis was also impaired without affecting exocytosis." (PMID 38559229, 2024). "Previous studies suggested that biallelic SYNJ1 mutations cause autosomal recessive, early-onset parkinsonism and EOPD9–12." (PMID 38853950, 2024). "Patients with autosomal recessive mutations of Synj1 developed Parkinson’s symptoms during the third decade of life." (PMID 39477959, 2024). "Several Parkinson’s disease causative mutations have been found in proteins functioning in synaptic vesicle endocytosis (e.g., SYNJ1, DNAJC6 (DnaJ heat shock protein family (Hsp40) member C6), SNCA (synuclein alpha) and LRRK2 (leucine rich repeat kinase 2))." (PMID 37067454, 2024). "The SYNJ1 gene’s product is key in synaptic vesicle dynamics, with mutations known to lead to early-onset Parkinson’s disease or DEE53, based on the affected protein domain." (PMID 39624497, 2024). "Recently, missense mutations including R258Q, R459P and R839C in PARK20/SYNJ1 have been discovered in families with early onset parkinsonism." (PMID 37072173, 2023). "Overexpression of another protein mutated in Parkinson’s disease, Synaptojanin-1, known to bind and metabolize specific phosphoinositides, rescues the DNAJC6/Auxilin lipid alterations, the neuronal function defects and neurodegeneration." (PMID 36739293, 2023). "Missense mutations in the Synj1 gene encoding Synaptojanin1 (Synj1), a neuron-enriched lipid phosphatase, have been linked to Parkinsonism with seizures." (PMID 34126070, 2021). "At present, 12 families with atypical Parkinsonism and biallelic SYNJ1 variants have been described." (PMID 34630269, 2021). "In conclusion, this study has extended the mutational and clinical spectrum of SYNJ1 associated with EO typical or atypical parkinsonism and suggests that the screening of this gene should be considered in isolated cases and in patients with a later AO." (PMID 33841314, 2021). "Complementary work in primary hippocampal culture and C. elegans has shown that the Parkinson-associated mutation in Synj1 SAC1 domain affects the localization of ATG9, which abnormally accumulates in subsynaptic foci." (PMID 34988081, 2021). "The human phosphatidylinositol 5-phosphatase synaptojanin-1, which has already been independently confirmed to be implicated in Parkinson’s and Alzheimer’s disease, was among those identified." (PMID 32419904, 2020). "Apart from being a potential drug target for Alzheimer’s disease, Down syndrome, and TBC1D24-linked epilepsy, loss-of-function mutations in Synj1 also lead to disease, including epilepsy and Parkinson’s disease." (PMID 33349335, 2020). "It was identified as a potential drug target for Alzheimer’s disease, Down syndrome, and TBC1D24-associated epilepsy, while also loss-of-function mutations in Synj1 are associated with epilepsy and Parkinson’s disease." (PMID 33349335, 2020). "Among genetic PD, PARK20 is a rare autosomal recessive juvenile Parkinson’s form due to mutations in Synaptojanin1 (Synj1), a phosphatidylinositol phosphatase (PtdInsPP)." (PMID 31316342, 2019). "On the other hand, variant in SYNJ1 gene was found to be associated with the heritable form of Parkinson’s disease (PD)." (PMID 31592138, 2019).
Parkinsonism (continued). "Only one deleterious variant, which is rs398122403 (R258Q) in SYNJ1 gene, was previously reported to be associated with Parkinson’s disease (PD)." (PMID 31592138, 2019). "Animal study has shown that mutations in the Sac phosphatase domain of SYNJ1 led to Parkinson’s-like neurological features and an increase in the levels of PD-associated proteins; auxilin, which has a similar role to synaptojanin-1in endocytosis and PARKIN." (PMID 29700661, 2018). "After being investigated as a candidate gene in bipolar disorder, Down's syndrome, and Alzheimer's disease with varying success, SYNJ1 was identified as the causative gene in three families with early-onset atypical Parkinsonism." (PMID 25302295, 2014). "SYNJ1 and auxilin-1 mutated patients show common features of early-onset Parkinsonism and seizures with other atypical symptoms." (PMID 25302295, 2014). "One missense mutation in one of SYNJ1 functional domains was recently incriminated in an autosomal recessive form of early-onset Parkinson's disease (PD)." (PMID 25302295, 2014). "A mutation in the SYNJ1 gene has been attributed to parkinsonism and dopaminergic dysfunction." (PMID 39050701, 2024). "Previous studies have suggested that rare biallelic SYNJ1 mutations may cause autosomal recessive parkinsonism and Parkinson’s disease (PD)." (PMID 38853950, 2024). "The Parkinsonism-linked R839C mutation, which has a more profound impact on the phosphatidylinositol phosphate metabolism than the R258Q mutation, is reported for the first time to promote basal level autophagosome formation that mimicked Synj1 deletion." (PMID 34126070, 2021). "Our findings expand the mutational spectrum and phenotypic profile of SYNJ1-related parkinsonism." (PMID 33841314, 2021). "Several mutations in synaptojanin-1 have also been linked to early onset Parkinsonism." (PMID 31941659, 2020). "Mutations in the human SYNJ1 gene are associated with both Parkinson’s disease (PD) and EIEE." (PMID 32899411, 2020). "Also responsible for early-onset PD, SYNJ1 mutations cause atypical parkinsonism with a number of features, such as dystonia, oculomotor apraxia, dementia, and seizures." (PMID 29163333, 2017). "In addition, mutations in SynJ1 have recently been linked to a human familial early-onset Parkinsonism." (PMID 24392132, 2014). "To date, several different mutations in the SYNJ1 gene have been described in several families from different countries, including Iran, Italy, India, Tunisia, Algeria, Senegal, Germany, China, and France, presenting early-onset PD, atypical parkinsonism, and JP, suggesting a mutational hotspot." (PMID 39273702, 2024). "In addition to roles in AD, mutations in SYNJ1 have been associated with early-onset atypical-Parkinson’s disease, suggesting that SYNJ1 manipulation may also prove beneficial in PD." (PMID 33841102, 2021). "We identified heterozygous variants in genes associated with recessive PD and parkinsonism, including one in DNAJC6, six in VPS13C, two in SYNJ1, three in PLA2G6 and one in FBXO7 in early-onset cases." (PMID 39867380, 2025). "Parkinsonism has been associated with either autosomal dominantly (α-synuclein, LRRK2, VPS35, EIF4G1) and recessively (PARK2, PINK1, DJ-1, SYNJ1, and PLA2G6) inherited mutations." (PMID 40278411, 2025). "We previously showed that Parkinson’s disease-causative mutations in LRRK2 and SYNJ1 alter synaptic autophagy." (PMID 37067454, 2024). "Recently, missense mutations of SYNJ1 encoding the SAC1 and 5’-phosphatase domains have been found in families with hereditary early-onset Parkinsonism." (PMID 37072173, 2023). "The pathogenesis of SYNJ1-related parkinsonism has been studied in zebrafish, Drosophila, and rodent models." (PMID 37047309, 2023). "Our work suggests specific lipid changes to be central to synaptic and neuronal dysfunction in DNAJC6/Auxilin- and Synj1-induced Parkinsonism." (PMID 36739293, 2023).
Parkinsonism (continued). "Aux-KO mice have phenotypic manifestations that resemble those of SJ1-KIRQ mice, and both of them recapitulate some of the manifestations of human Parkinsonism patients carrying mutations in the DNAJC6/PARK19 and the SYNJ1/PARK20 genes." (PMID 36792618, 2023). "Mutations in the SYNJ1 gene, also known as the PARK20 gene, have been associated with monogenic parkinsonism with autosomal recessive inheritance and predominant postural instability, dystonia, cognitive impairment, and seizures." (PMID 35557621, 2022). "Synaptojanin-1 is a phosphoinositide phosphatase and importantly, mutations to the SYNJ1 gene, encoding synaptojanin-1, are associated with Parkinsonism (symptoms of bradykinesia and either rest tremor, rigidity or both)." (PMID 36358947, 2022). "SYNJ1-related diseases are heterogeneous in terms of their symptoms, ranging from EO typical PD to EO complex parkinsonism (both designated PARK20), and severe neurodegeneration with intractable seizures." (PMID 33841314, 2021). "Recent studies have revealed a tight link between neurodegenerative diseases, particularly Parkinson’s disease, and proteins that participate in synaptic vesicle endocytosis, such as auxilin, synaptojanin 1, and endophilin." (PMID 34569930, 2021). "Examples are PICALM/CALM contributing to Alzheimer’s disease pathology, C9ORF72 implicated in ALS and FTD and several genes linked to Parkinson’s disease such as LRRK2, VPS35, SNCA, Synj1 and EndoA." (PMID 34988081, 2021). "For example several mutations in SYNJ1 have been identified in patients with early onset Parkinson's disease PARK20." (PMID 33584199, 2020). "Further atypical forms of parkinsonism, with juvenile onsets, include genes implicated in lysosomal function (ATP13A2) and synaptic vesicle endocytosis (SVE) pathway (DNAJC6 and SYNJ1)." (PMID 33381501, 2020). "Thus, our findings provided important mechanistic insight for Synj1-regulated DAT trafficking integral to dysfunctional DA signaling in early parkinsonism." (PMID 38559229, 2024). "Furthermore, whole-exome sequencing did not identify pathogenic (or likely pathogenic) variants in the PINK1, SYNJ1, and PODXL genes and other known genes associated with early-onset parkinsonism." (PMID 39332416, 2024). "SYNJ1-related parkinsonism is generally characterized by disease onset in the third decade of life." (PMID 37047309, 2023). "Thus, our work suggests a novel mechanism for Synj1-related Parkinsonism involving astrocyte dysfunction." (PMID 34126070, 2021). "Loci associated with rare monogenic forms of Parkinson’s disease, or more complex disorders with a prominent component of parkinsonism, also encode proteins involved in vesicle trafficking: VPS35, ATP13A2, PLA2G6, DNAJC6, SYNJ1, and VPS13C." (PMID 33556113, 2021). "These include genes such as NUSAP1 and MS4A6A that are associated to glomerulonephritis, an IgA nephropathy; GPBAR1 that is highly expressed in intestinal monocytes of patients with inflamed Crohn's disease, and; SYNJ1 and PLD3 that are both associated to Parkinson's disease and Alzheimer's disease." (PMID 26338775, 2015). "Screening of all exons in 138 additional patients, among which 46 presented with complex early-onset Parkinsonism, did not identify any other homozygous or compound heterozygous mutation in SYNJ1." (PMID 25302295, 2014). "Based on its molecular function, SYNJ1 could play a role in Parkinson's disease molecular mechanism." (PMID 24688734, 2013). "In particular, we envisage that more detailed investigations on experimental models of GBA1-, SYNJ1-, SYPH1-, TMEM230-, Parkin-, PINK1-, ATP13A2-, FBXO7- and SYT11-associated parkinsonism could provide new insight into the pathophysiological mechanisms leading to PD that may involve Rab dysfunction." (PMID 36009486, 2022). "Moreover, atypical or complex parkinsonism may be due to mutations in genes such as ATP13A2, DCTN1, DNAJC6, FBXO7, PLA2G6, and SYNJ1." (PMID 35328025, 2022).
Parkinsonism (continued). "The Parkinsonism R839C mutation that disrupts 60% of the 5’-phosphatase activity enhanced autophagosome formation at the basal level, mimicking that of Synj1 KO astrocytes; whereas the R258Q mutation that does not affect the 5’-phosphatase activity showed minimal impact." (PMID 34126070, 2021). "Finally, DNAJC6, SYNJ1 and SH3GL2 are associated with the disruption of synaptic vesicle endocytosis, which contributes to mitochondrial dysfunction and is thus related to the pathogenesis of Parkinson’s disease." (PMID 33686350, 2021). "Interestingly, several PD-associated genes such as Pink1, Parkin, and Synj1, associated with early onset parkinsonism without robust evidence of synucleinopathy, did not impact synuclein aggregation in this screening assay." (PMID 30927072, 2019). "The mechanistic link between Synj1 and early-onset parkinsonism is still unknown." (PMID 29515184, 2018). "Synaptojanin 1 (SYNJ1) is a protein-coding gene related to developmental and epileptic encephalopathy and Parkinson's disease." (PMID 39991576, 2025). "The mutants included in this study are ‘classical’ Parkinson disease genes, like LRRK2 and PINK1, and Parkinsonism genes that affect vesicle trafficking processes, including SYNJ1, DNAJC6/Aux. and RAB39B." (PMID 40178224, 2025). "Two main phenotypes have been associated with SYNJ1 pathogenic variants: a severe disorder with neonatal refractory epilepsy and neurodegenerative course (MIM #61738932) and early-onset Parkinsonism (MIM #61553033), with/without epilepsy." (PMID 36835207, 2023). "Other genes such as APT13A2, PLA2G6, FBXO7, and the more recently identified DNAJC6, SYNJ1, and VPSC13 are usually related to younger onset Parkinsonism, complicated by atypical motor and non-motor phenotypes." (PMID 34630269, 2021).